SRSF2 (serine and arginine rich splicing factor 2)
Diseases named in the same sentence as SRSF2 in open-access papers (continued):
Sharing a sentence is not in itself a finding about the gene and the disease.
leukemia (56 papers, 2009 to 2026). A malignant (clonal) hematologic disorder, involving hematopoietic stem cells and characterized by the presence of primitive or atypical myeloid or lymphoid cells in the bone marrow and the blood. "Subsequent genome-wide association studies using these continuous risk scores uncovered novel disease-associated loci, including PPP1R15A for T2D and JMJD6/SRSF2 for leukemia, that were missed by traditional binary case definitions." (PMID 41627341, 2026). "Collectively, our results show that Runx1/RUNX1 loss reduces sensitivity to CHK1 inhibitors across systems: Srsf2P95H and U2AF1S34F mouse progenitors, SRSF2-mutant patient samples with RUNX1 mutation, and human leukemia lines with SRSF2 mutation (K562, KO52)." (PMID 41279606, 2025). "A previous study demonstrated the efficacy of a spliceosome inhibitor in SRSF2-mutated leukemia in a murine model." (PMID 40562788, 2025). "Among these components, serine/arginine-rich splicing factor 2 (SRSF2) has recently been identified as a high-risk factor in leukemia; this protein is important for RNA binding and splice site selection." (PMID 40562788, 2025). "The fact that SRSF2 mutations are the first events in a high-risk leukemogenic process highlights their potential as targets for preventing leukemia." (PMID 38558935, 2024). "Recently, a notable study identified another novel RNA m5C methylation binding protein, SRSF2, and revealed its association with leukemia development." (PMID 39445003, 2024). "Further research found that the SRSF2P95H mutation in leukemia inhibits SRSF2 recognition of m5C, affecting mRNA alternative splicing mediated by SRSF2, and leukemia patients with impaired SRSF2‐m5C binding have poor prognosis." (PMID 39445003, 2024). "This rationale was successfully tested for one such splicing inhibitor, E7107, which decreased leukemia burden in mice carrying SRSF2 mutations." (PMID 38558935, 2024). "This is in agreement with previous findings, showing that E7107 substantially reduced leukaemia cell burden in an isogenic mouse model carrying an Srsf2 P95H mutation as well as in PDX models from patients harbouring SRSF2 mutations compared to WT models." (PMID 35582381, 2021). "SRSF2 mutations were also associated with a lower leukemia-free survival in MPN, more particularly in PMF." (PMID 32784800, 2020). "E7107 treated isogenic murine myeloid leukemias showed preferential cell death of leukemia cells with mutated Srsf2 compared to wild-type Srsf2." (PMID 32481522, 2020). "Several studies have provided evidence for the adverse impact of somatic mutations in ASXL1, EZH2, IDH1/2, and SRSF2 on shorter OS or leukemia-free survival in patients with PMF." (PMID 32781570, 2020). "In both univariate and multivariable analysis, leukemia-free survival was adversely affected by SRSF2 mutations (HR 4.7, 95% CI 1.3–16.9), very high-risk karyotype (HR 7.9, 95% CI 1.9–32.1), and circulating blasts ≥2% (HR 3.9, 95% CI 1.4–11.0)." (PMID 29515114, 2018). "Importantly, we found that these glycation events attenuate SRSF2's RNA binding and alter RNA splicing, phenocopying a recurrent leukemia oncogenic SRSF2 mutation, P95H." (PMID 42108729, 2026). "To determine whether SRSF2 mutations alone are sufficient to sensitize leukemia cells to ATR/CHK1/WEE1 inhibition, we modeled the mutations in two complementary systems: (i) isogenic human K562 cell lines and (ii) knock-in mouse bone marrow progenitors." (PMID 41279606, 2025). "Next, we tested whether RUNX1 loss alters CHK1-inhibitor response in human SRSF2-mutant leukemia cells." (PMID 41279606, 2025).
leukemia (continued). "To determine whether SRSF2 mutations are sufficient to sensitize leukemia cells to inhibition of ATR, CHK1, and WEE1, we tested the sensitivity of ten isogenic SRSF2 mutant and four wild-type K562 clones to inhibitors of these kinases." (PMID 41279606, 2025). "Based on the findings of previous studies and our data, we believe that SRSF2 mutation may be associated with leukemia transformation and inferior survival in MDS/MPN-SF3B1-T patients." (PMID 38714876, 2024). "Among the six patients with SRSF2 mutations, one patient progressed to leukemia and subsequently died, whereas another three patients died from unknown causes." (PMID 38714876, 2024). "Mutations in SRSF2 were linked to reduced overall and leukemia-free survival." (PMID 39034387, 2024). "SRSF2 associated with JAK2 V617F correlates with a reduced leukemia free-survival." (PMID 35562964, 2022). "Although mutations in genes required for splicing and methylation commonly occur in leukemia, and a mutation in a splicing factor (SRSF2) has been shown to impact methylation in acute myeloid leukaemia, the interaction of these two processes has not been described in CLL patients carrying SF3B1mut." (PMID 34502260, 2021). "In the CTRL-ROY group, enrichment was significant for “leukemia” and “acute leukemia” terms (NES = 2.12, Q = 0.03), driven by key myeloid malignancy-associated genes DNMT3A, IDH1, SRSF2, and TET2." (PMID 41371958, 2026). "The remaining unremitted children included one with DEK::NUP214, one with secondary leukemia associated with KAT6A::CREBBP, and another with AXSL1 and SRSF2." (PMID 41264489, 2025). "For example, SRSF2-mutant leukaemia cells are more sensitive than wild-type cells to inhibitors targeting components of the splicing network, such as the SF3B complex." (PMID 37778382, 2023). "Recently, it was suggested that SF3B1, SRSF2, ASXL1, TET2, and DNMT3A gene mutations contribute to the risk of MDS evolution to leukemia and also influence therapy response and overall survival." (PMID 36982819, 2023). "More than 80% of patients with overt-PMF carry variants/mutations other than JAK2/CALR/MPL, in particular high-risk mutations which are associated with overall prognosis and leukemia-free survival (ASXL1, SRSF2, IDH1/IDH2, EZH2)." (PMID 36580136, 2023). "So far ASXL1, SRSF2, IDH2 have been identified as unfavourable risk factors affecting overall (OS), leukemia-free (LFS), or myelofibrosis-free survival (MFFS) in PV." (PMID 36242602, 2023). "A previous study has reported that in leukemia, mutant SRSF2 cells were more sensitive to E71079, a splicing-altering compound that binds to the SF3B complex, than wild-type SRSF2 cells." (PMID 38015716, 2023). "The presence of STAG2, SRSF2 and RUNX1 mutations, alone or in combination, shortening both the time to leukemia transformation and the OS within MDS patients with isolated +8." (PMID 37568638, 2023). "Significant association was also noted between SRSF2, IDH2, and RUNX1 for leukemia-free survival, and SRSF2 and RUNX1 for myelofibrosis-free survival." (PMID 37745842, 2023). "A closer look into the mutations that persisted following therapy (at remission) in responders revealed that they were in genes associated with pre‐leukaemia (ASXL1, DNMT3A, IDH2, SRSF2 and TET2)." (PMID 36051087, 2022). "In PV patients, the presence of ASXL1, SRSF2, and IDH1 seems to be associated with poorer overall survival and leukemia-free survival." (PMID 35562964, 2022). "While being infrequent in PV and ET patients, SRSF2 mutations occur in 8–22% of PMF and BP, where predict for poor overall and leukemia-free survival." (PMID 34440731, 2021). "Several NGS studies observed shorter OS or leukemia-free survival in MF patients with mutations in ASXL1, SRSF2, or EZH2." (PMID 32781570, 2020).
leukemia (continued). "In conclusion, SF3B1, SRSF2, ZRSR2 and U2AF1 spliceosomal mutations affect overall and leukemia-free survival in MPN." (PMID 32784800, 2020). "In PV, ASXL1 and SRSF2 were associated with inferior OS, SRSF2 and IDH2 with shorter leukemia-free survival and SRSF2 with shorter myelofibrosis-free survival." (PMID 32781570, 2020). "We generated to generate cell lines that stably express either wild-type or SRSF2 mutants with K562 cells, a myelogeneous leukemia cell line." (PMID 31040863, 2019). "H3B-8800 is a small molecule modulator of spliceosome complex and has been shown to lower leukemia burden in SRSF2-P95H mutant mice." (PMID 30275952, 2018). "E7107, a spliceosome inhibitor, has been shown to differentially inhibit splicing more in SRSF2-mutant cells leading to decreased leukemia burden in mice." (PMID 30275952, 2018). "E7107, a spliceosome inhibitor, has shown to differentially inhibit splicing more in SRSF2-mut cells leading to decreased leukemia burden in mice." (PMID 30275952, 2018). "We observe that age is highly connected to the mutations SF3B1, SRSF2, and TET2, and the chromosomal abnormality -5/del(5q), which may reflect leukemias deriving from previous MDS clones, resulting as an accumulation of genetic driver events later with age." (PMID 40301336, 2025). "Although prior studies have reported that mutations in SF3B1, SRSF2, and U2AF1 cause global R-loop augmentation, to our knowledge, no studies thus far have assessed cen-R-loop levels or their roles in the pathogenesis of SF mutant leukemia." (PMID 37463047, 2023). "Given the promising results in murine leukemia models with co-occurring mutations, we then evaluated the ex vivo activity of TP-0903 and TKIs in human primary samples with coexisting recurrent mutations (e.g., FLT3-ITD, IDH1/2, ASXL1, DNMT3A, NPM1, and SRSF2)." (PMID 33268594, 2020). "Using a candidate gene approach, five mutated genes including ASXL1, SRSF2, EZH2, IDH1, and IDH2, which are reported to occur in 25–30% of all PMF patients, were associated with shorter OS and leukemia-free survival (LFS), defining a high-molecular risk (HMR) category." (PMID 31013941, 2019). "In the Mayo Clinic group, leukemia-free survival was associated with IDH1 and SRSF2 mutations." (PMID 37745842, 2023). "Unlike in PMF, the presence of additional high-risk mutations (ASXL1, EZH2, IDH1, IDH2 or SRSF2, as single or multiple mutations) was not correlated with reduced leukaemia-free survival or indeed overall survival, with the exception of mutations in SRSF2, associated with reduced survival." (PMID 34068690, 2021). "Our results suggest that modulating the cytoskeleton by RKI-1447 and possibly other microtubule modifiers can take advantage of the abnormal cytoskeleton induced by SRSF2 Mut and open new ways to treat AML/MDS and pre-leukemia." (PMID 38558935, 2024). "The concurrence of genetic changes in IDH2 and SRSF2 among individuals with AML results in synchronized impacts on the epigenome and RNA splicing, which play a role in the development of leukemia." (PMID 39034387, 2024). "For example, human myeloid and leukemia cells engineered to carry heterozygous mutations in both SF3B1 and SRSF2 are not viable." (PMID 40624356, 2025).
acute myeloid leukemia (47 papers, 2014 to 2026). Acute myeloid leukemia (AML) is a group of neoplasms arising from precursor cells committed to the myeloid cell-line differentiation. "A well-documented example is the SR protein, SRSF2, frequently mutated in patients with acute myeloid leukemia (AML)." (PMID 33926465, 2021). "SRSF2, one of the SR proteins, is frequently mutated in acute myeloid leukemia (AML)." (PMID 37342192, 2023). "Mutations of SRSF2 are more frequently observed in secondary acute myeloid leukemia (AML) derived from MDS or MPN." (PMID 39584923, 2024). "An analysis of transcriptomes from 982 acute myeloid leukemia patients showed that RNA variants in isocitrate dehydrogenase (NADP(+)) 2 (IDH2) and serine- and arginine-rich splicing factor 2 (SRSF2) promoted leukemogenesis and epigenome and RNA splicing." (PMID 39408729, 2024). "For patients with a history of or a new diagnosis of acute myeloid leukemia (AML) at the time of ordering (n = 52), the most commonly mutated genes were RUNX1, SRSF2, and IDH2 (each with 16 variants)." (PMID 39691272, 2024). "A well-characterized example is SRSF2, a splicing factor with a stimulatory effect on NMD, which is commonly mutated in Pro95 in patients affected by acute myeloid leukemia (AML)." (PMID 33321981, 2020). "However, similar to NPM1 and FLT3 mutations in acute myeloid leukemia (AML), SRSF2 mutations seem to occur later in the development of myeloid neoplasms than TET2 mutations." (PMID 27029036, 2016). "Studies have shown that the abnormal expression of the SRSF2 gene is strongly correlated with acute myeloid leukemia (AML), liver cancer, lung cancer, and other diseases." (PMID 39330852, 2024). "In acute myeloid leukemia (AML) patients with IDH mutations, frequent mutations in splicing factor mutations are shown including SRSF2 and SF3B1." (PMID 35252202, 2022). "Targeted NGS analysis performed at diagnosis and focused on acute myeloid leukemia driver genes is helpful since the presence of pathogenic mutants (IDH1 p.Arg132His, SRSF2 p.Pro95Thr, WT1 p.Cys393Ter in this study) could represent additional risk factors or opportunities for targeted therapy." (PMID 30848074, 2019). "The SRSF2 mutation strongly correlated with old age (P < 0.001), while the mutation status of SF3B1 did not affect overall survival (OS), progression-free survival (PFS), or acute myeloid leukemia (AML) transformation." (PMID 26115659, 2015). "We then analyzed patients with chronic myelomonocytic leukemia (CMML) or acute myeloid leukemia (AML) harboring TET2 and SRSF2 comutations." (PMID 40877435, 2025). "Further research is warranted to elucidate the genetic predispositions that may facilitate the transformation of leukemic MPNs into acute myeloid leukemia (AML), with emphasis on genes such as ASXL1, IDH1, IDH2, and SRSF2, among others." (PMID 39682300, 2024). "Non-driver mutations, such as those in ASXL1, EZH2, TET2, SRSF2, and IDH1/IDH2, have been found to exacerbate disease severity, accelerate progression, and increase the risk of transformation to acute myeloid leukemia (AML)." (PMID 39434124, 2024).
myeloid neoplasm (43 papers, 2012 to 2026). Proliferation of myeloid cells originating from a primitive stem cell. "In summary, this study demonstrated that co-occurring mutations of Asxl1 and Srsf2 accelerate the development and enhance the severity of myeloid malignancies." (PMID 38017104, 2024). "Regarding haematopoietic malignancies, mutations of SF3B1 and SRSF2 are frequently observed in myeloid neoplasms such as myelodysplastic syndrome." (PMID 38918373, 2024). "Each SF is also associated with a distinct pattern of mutations in other genes commonly detected in myeloid malignancies, as in the case of SRSF2 mutations with TET2 mutations in CMML and with RUNX1, IDH2, and ASXL1 mutations in AML." (PMID 31766606, 2019). "We also observed a high frequency of ASXL1, SETBP1 and SRSF2 mutations in myeloid neoplasms associated with i(17q)." (PMID 26883102, 2016). "Several studies have highlighted co-mutation of ASXL1 and SRSF2 in subsets of myeloid neoplasms, for which the clinical implications remain unclear." (PMID 40562788, 2025). "To further assess the consequences of SRSF2 mutation for the cellular proteome in myeloid neoplasms, we performed quantitative mass spectrometry (qMS) with a focus on the mitochondrial proteome by using human proteome (UniProtKB) and mitochondrial (MitoCarta3.0) databases for protein identification." (PMID 38713535, 2024). "A higher frequency of SRSF2 mutations in this study might be partially due to age effect; elder patients were also enrolled in this cohort and SRSF2 mutation is closely associated with older age in myeloid neoplasm." (PMID 26812887, 2016). "Isolated isochromosome 17q, i(17q), accounts for less than 1% of myeloid neoplasms, including AML, MDS, and myeloproliferative neoplasms (MPN), and frequently harbors mutations in SETBP1, ASXL1, SRSF2, and NRAS." (PMID 41148513, 2026). "ETNK1 mutation is an early event in myeloid neoplasms, often co-occurring with ASXL1, TET2, EZH2, RUNX1, and SRSF2 mutations." (PMID 40074445, 2025). "In the absence of these three major driver mutations, screening for other mutations associated with myeloid neoplasms, such as ASXL1, EZH2, TET2, IDH1, IDH2, SRSF2, and SF3B1, can help establish the clonal nature of the disease." (PMID 41514563, 2025). "NGS is essential for this diagnosis, as it enables detection of at least one somatic mutation in genes commonly mutated in myeloid neoplasms (e.g., DNMT3A, TET2, ASXL1, SF3B1, SRSF2, etc.)." (PMID 41464583, 2025). "Our study indicated that MDS/MPN is characterized by mutations commonly identified in myeloid neoplasms, with TET2 (52%) being the most frequently mutated gene, followed by ASXL1 (38.7%), SRSF2 (34.7%), and JAK2 (19.7%), among others." (PMID 39337700, 2024). "Our results demonstrated that MDS/MPN is characterized by the presence of mutations commonly identified in myeloid neoplasms, such as TET2, ASXL1, SRSF2, and SF3B1." (PMID 39337700, 2024). "The majority of ASXL1-mutated patients had other concurrent gene mutations, and splicing factors (SRSF2, U2AF1, ZRZR2, SF3B1) were most frequently mutated in myeloid malignancies." (PMID 38017104, 2024). "The most commonly mutated spliceosome genes in myeloid malignancies, SF3B1, SRSF2, and U2AF1, are also frequently identified in individuals with CHIP." (PMID 38028538, 2023). "Frequent somatic mutations in splicing factors including SF3B1, SRSF2, and U2AF1 were discovered in myeloid malignancies as well as solid tumors." (PMID 37810965, 2023). "ASXL1mt in myeloid neoplasms were considered to be ubiquitously accompanied by mutations of RUNX1, SRSF2, STAG2, NRAS, or IDH2, in addition to wild‐type NPM1 and FLT3,14, 21, 22, 28 which was aligned with the mutation profile in our cohort." (PMID 38146893, 2023). "Murine models with conditional heterozygous expression of splicing factor (SF) mutations (SF3B1, U2AF1, SRSF2, ZRSR2) have confirmed the causative effects of RNA splicing dysregulation in the pathogenesis of myeloid malignancies and CLL." (PMID 37463047, 2023).